RNU5E-9P (RNA, U5E small nuclear 9, pseudogene)
Gene: Small nuclear RNA gene on chromosome 2 (178,142,548 to 178,142,651, forward strand). Ensembl gene ENSG00000223096.
Homologues: Orthologues: chimpanzee U5 (100% identical), macaque U5 (89% identical). Paralogues in human: RNU5E-10P (84% identical), RNU5E-6P (82% identical), RNU5E-8P (81% identical), RNU5E-7P (78% identical), RNU5A-6P (77% identical), RNU5E-5P (77% identical), RNU5F-4P (77% identical), RNU5B-4P (76% identical), RNU5E-4P (76% identical), RNU5A-3P (75% identical), RNU5A-4P (73% identical), RNU5A-5P (72% identical), and 13 more.